CDK4 (cyclin dependent kinase 4)
Diseases named in the same sentence as CDK4 in open-access papers (continued):
Sharing a sentence is not in itself a finding about the gene and the disease.
ovarian carcinoma (continued). "Also, lncRNA-KB-1471A8.2 was reported to be downregulated in ovarian cancer tissues and chemoresistant ovarian cancer cells and acted as tumor suppressor gene by inhibiting the expression of CDK4." (PMID 33302997, 2020). "Additionally, it was demonstrated that sulforaphane is able to reduce the proliferation capacity of human (SKOV3) and mouse (C3 and T3) ovarian cancer cell lines by downregulating cyclin D1 and cyclin-dependent kinases 4 and 6 (CDK4 and CDK6)." (PMID 32213900, 2020). "In ovarian cancer, CDK4/6 inhibitors have shown promise in vitro." (PMID 29644000, 2018). "Clinical data regarding CDK4/6 inhibition in ovarian cancer are sparse." (PMID 29644000, 2018). "In our study, mutational analysis of TCGA ovarian cancer data has shown that a significant percentage of patients have mutations or dysregulated expression of CDKN2A, CDK4, CDK6, or CCND1 that would likely make them good candidates for CDK4/6 inhibitor therapy." (PMID 29644000, 2018). "Nevertheless, in ovary cancer, it is known that the increase in the percentage of cells in G1 in response to melatonin (range from 0 to 800 μM) is associated with a downregulation of cyclin-dependent kinases 2 and 4 (CDK2 and CDK4)." (PMID 30386380, 2018). "Furthermore, CDK4 is overexpressed in 14% to 15% of ovarian tumors and its activity in malignant ovarian tumors is significantly greater than in benign tumors." (PMID 23236518, 2012). "However, currently, there is no single compound that could combine PARP and CDK4/6 inhibition, which prompted us to develop new dual-targeting compound to improve the efficacy of PARP and CDK4/6 inhibits in breast and ovarian cancers." (PMID 35270034, 2022). "Interestingly, the efficacy of ZC-22 is even higher than the combination of PARPi Olaparib and CDK4/6i Abemaciclib in most breast and ovarian cancer cells, suggesting that it may be an effective alternative for the PARPi and CDK4/6i combination therapy." (PMID 35270034, 2022). "Thus, any strategies or compounds that could combine PARP and CDK4/6 inhibition may improve the clinic outcomes and benefit more patients with breast or ovarian cancer." (PMID 35270034, 2022). "In this study, RPS6 knockdown resulted in decreased Cyclin E, CDK2, Cyclin D1, CDK4, and CDK6 levels, and reduced Rb phosphorylation, thus hindering the transition from G0G1 to S phase, causing most cells to be blocked in G0G1 phase, thereby inhibiting ovarian cancer cell growth." (PMID 32862831, 2020). "However, the effects of CDK4/6is on the tumor microenvironment (TME) of ovarian cancer and whether these inhibitors can enhance the efficacy of immunotherapy are still unknown." (PMID 32929370, 2020). "Based on these studies, CDK4/6 inhibition could be a promising strategy in ovarian cancer." (PMID 32929370, 2020). "Paradoxically, although CDK4/6 inhibition (CDK4/6i) have cytostatic effects, TNBC and ovarian cancer cells treated with doxorubicin, paclitaxel, or carboplatin were resistant to cytotoxic effects and the associated cell death in response to CDK4/6 inhibition." (PMID 39788939, 2025). "Another promising combination is the PARP inhibitor, olaparib, with the cyclin-dependent kinases 4/6 (CDK4/6) inhibitor, palbociclib, which had synergistic effects against MYC-overexpressing ovarian cancer cells." (PMID 40862711, 2025). "A decrease in important elements in this pathway, like P-PI3K, P-AKT, CCND1, CDK4, and P-RB, supports the idea that Kirenol could potentially inhibit this signaling cascade, providing new understanding of how it works and strengthening its potential as a hopeful treatment for ovarian cancer." (PMID 38415456, 2025). "Chen and colleagues found that CDK4/6is potentiated the secretion of IFN-γ and the interferon-stimulated gene (ISG) response in ovarian cancer, which upregulated the expression of antigen-presenting molecules." (PMID 39593745, 2024).
ovarian carcinoma (continued). "MiR-1 can suppress the growth of ovarian cancer cells by targeting p-Akt, p-ERK1/2, p-Rb, and CDK4 in HO-8910PM cells and suppress c-Met expression, which shows its inhibitory effect." (PMID 38504949, 2024). "Fascaplysin treatment also reduced the expression levels of cyclin D1, CDK4, Bcl-2 and VEGFA, demonstrating that fascaplysin showed anti-tumor activity on ovarian cancer cell lines by inhibiting CDK4." (PMID 37103365, 2023). "Studies have shown that CDK4/6 inhibition combined with PD-1 blockade treatment has higher CXCL10 and CXCL13 levels and CD8 + and CD4 + T cell activity than monotherapy-treated ovarian cancer." (PMID 37005667, 2023). "Other amplified oncogenes frequently found in epithelial ovarian cancer were ERBB2, STAT3, PIK3C2B, CDK2, and CDK4, as well as SWI/SNF chromatin modification complex genes, including ARID1A and SMARCC1." (PMID 36430324, 2022). "After 48 h of bexarotene treatment, the levels of CDK4, CDK6, Cyclin D1, and phospho-RB decreased in both ovarian cancer cell lines." (PMID 35778597, 2022). "Altogether, our study has demonstrated the potency of a novel CDK4/6 and PARP dual inhibitor, which can potentially be developed into a monotherapy or combinatorial therapy with cisplatin for breast and ovarian cancer patients with HR proficiency." (PMID 35270034, 2022). "Recently, a new and very efficient CDK4/6–RB1 axis blocker has emerged as an antitumor drug thanks to its interesting efficacy in breast and ovarian cancers, among other malignant neoplasms." (PMID 35681689, 2022). "Recently, therapeutic synergy for combination of PARPi and CDK4/6i has been demonstrated in MYC highly expressed breast and ovarian cancers with HR proficiency, which provides a new synthetic lethal strategy for treatment of these cancers regardless HR status." (PMID 35270034, 2022). "Recently, BRD4 inhibitor JQ1 and CDK4/6 inhibitor palbociclib have been shown to inhibit HR and sensitize BRCA1/2 wild-type ovarian cancers and other cancers to PARPi." (PMID 36539830, 2022). "The levels of p-RB, cyclin D1, cyclin E, CDK2, CDK4, or CDK6 by RPS6-KD were reduced in NSCLC cells, ovarian cancer cells, and drug-resistant melanoma cells." (PMID 35008473, 2021). "We and others have evaluated the expression of both CDK4 and CDK6 in epithelial ovarian cancers with interesting results." (PMID 34204543, 2021). "Consistently, the G0/G1 checkpoint regulators, such as cyclin D1, cyclin E, CDK2, CDK4, CDK6, and p-RB, are diminished by RPS6-KD in ovarian cancer cells." (PMID 35008473, 2021). "Here, we review the role of CDK4 and CDK6 complexes in ovarian cancer and propose the possible use of their inhibitors in the treatment of ovarian cancer patients with different types and stages of disease." (PMID 34204543, 2021). "The results of the western blot assay indicated that trichodermin significantly suppressed the expression of cyclin D1, CDK4, CDK2, p-Rb, and Rb in both ovarian cancer cell lines." (PMID 34065149, 2021). "shBTG2 caused a notable increase in the expression of the cell cycle proteins Cyclin D1 and CDK4, while GV-BTG2 decreased Cyclin D1, CDK4 and CDK2 expression in ovarian cancer cells." (PMID 34485119, 2021). "Our study highlights the capacity of XFC to specifically decrease Cdk4, Cyclin D3, and p27 expressions in chemoresistant SKOV-3 ovarian cancer cells." (PMID 31827554, 2019). "To validate the GSEA results, we then detected the levels of Cyclin D1, CDK4, p16, AKT, p-AKT, mTOR, p-mTOR, p70S6K1 and p-p70S6K1 in ovarian cancer cells with AE2 silenced." (PMID 28743911, 2017). "miR-506 can suppress the CDK4/6-FOXM1 signaling pathway, which is activated in the majority of ovarian carcinomas." (PMID 27542202, 2016). "The results demonstrated that following transfection of the WWOX gene, ovarian cancer stem cells expressed significantly lower levels of cyclin E, CDK2, cyclin D1 and CDK4 proteins than the empty plasmid group and the control group." (PMID 25891642, 2015).
ovarian carcinoma (continued). "We have directly compared the response and resistance mechanisms for CDK4/6 inhibition (PD0332991) and CDK2 inhibition (SNS032; dinaciclib) in a panel of ovarian cancer cell lines." (PMID 25557169, 2015). "For example, CDKN2B and CDK4 as well as EGFR and NF1 are involved in the RB and RTK signaling pathways, respectively and the CCNE1, MYC and RAD52 module in ovarian carcinoma is involved in cell cycle." (PMID 24565034, 2013). "Furthermore, the combination of CDK4/6is and anti-PD1/PD-L1 therapy achieved superior tumor control compared to monotherapy in cases of poorly immune-infiltrated ovarian cancer." (PMID 39593745, 2024). "To address this hypothesis, we have comprehensively evaluated the clinicopathological significance of the CDK2, CDK4, CDK6, cyclin D1, cyclin E1, RB1 and pRB1(Ser 795) protein expression in a clinical cohort of epithelial ovarian cancer." (PMID 38612869, 2024). "Genomic alterations in CDK4 and CDK6 have been reported in ovarian cancer." (PMID 38612869, 2024). "PCR and cytokine array methods were applied to detect cytokine and chemokine levels, which revealed that ID8 ovarian cancer cells secrete higher levels of CXCL10 and CXCL13 after CDK4/6i treatment resulting in increased lymphocytes infiltration in the tumor microenvironment." (PMID 35053457, 2022). "In addition, qRT-PCR results revealed the expression of CDK4, FGF5, MEIS1, and TES genes was significantly increased in CFP1-deleted ES-2 ovarian cancer cells." (PMID 35864225, 2022). "At the same time, cyclin-dependent kinases (CDKs) are becoming an important target in breast and ovarian cancer treatment, with various FDA-approved CDK4/6 inhibitors that have recently received more attention for their potential role in diet-induced obesity (DIO)." (PMID 35681689, 2022). "In conclusion, we developed a novel compound, ZC-22, as a CDK4/6 and PARP dual inhibitor, which displays high therapeutic potential for advanced breast and ovarian cancer patients regardless their HR status, either alone or in combination with platinum-based agents." (PMID 35270034, 2022). "Recently, several studies indicated that a combination of Olaparib with CDK4/6i displayed therapeutic synergy in MYC highly expressed breast and ovarian cancers with HR proficiency, which represents a new treatment paradigm in these cancers beyond HR-deficiency." (PMID 35270034, 2022). "Here, we will focus on the possible roles that the inhibition of two central regulators of cell cycle progression, namely CDK4 and CDK6, may play in the context of ovarian cancer." (PMID 34204543, 2021). "Finally, in ovarian cancer, MYC amplification predicted synergistic benefit from a combination of PARP inhibition with olaparib and CDK-4 inhibition with palbociclib." (PMID 34638300, 2021). "Moreover, the evaluation of the miR-124 overexpression in MSC exosomes has shown the proliferation inhibition of ovarian cancer cells by arrest induction in the S phase through the downregulation of Cyclin-Dependent Kinase 2 (CDK2), CDK4, and CDK6." (PMID 34307654, 2021). "For this aim, they screened 40 ovarian cancer cell lines for their sensitivity to palbociclib and identified the so-called Rb1-proficient cell lines, with low p16INK4A and CCNE1 expression, as the most responsive to CDK4/6i." (PMID 34204543, 2021). "Regulation of gene transcription by CDK4 and CDK6 has a well-established role in the regulation of senescence, through the phosphorylation of the transcription factor FOXM1 and described as an important event in melanoma and ovarian cancer." (PMID 34204543, 2021). "Aberrant activation of CDK4 and CDK6 is a common finding in ovarian cancer 16,17." (PMID 32929370, 2020). "The combined use of CDK4/6i and ICB may be beneficial, but the effects of CDK4/6is on the tumor immune microenvironment and whether they can synergize with ICB in treating ovarian cancer remain unknown." (PMID 32929370, 2020).
ovarian carcinoma (continued). "Accordingly, it is possible that the efficacy of inhibitors such as ribociclib (targeting CDK4/6, the activated binding partner of CCND2) may be underestimated in ovarian cancer PDX models with down-regulated CCND2 expression." (PMID 31004097, 2019). "A subset of ovarian cancer is known to overexpress CCNE1 or CCND1, suggesting that cell-cycle-targeted drugs such as palbociclib, a CDK4/6 inhibitor, may be effective in specific subsets of ovarian cancer." (PMID 31052165, 2019). "Together, these data suggest that CDK4/6 inhibition does not induce a truly senescent state in ovarian cancer cells." (PMID 29644000, 2018). "While Phase 1 (NCT03294694, NCT02897375) and Phase 2 (NCT02657928) trials of CDK4/6 inhibition in combination with other therapies in ovarian cancer have recently opened, no data is available yet from these studies." (PMID 29644000, 2018). "Inhibition of PCDGF by antisense PCDGF transfection could downregulate the expression of cyclin D1, CDK4 and MMP-2, and markedly reverses malignant phenotype of ovarian cancer." (PMID 17261172, 2007). "Cyclin-dependent kinases (CDK2, CDK4, CDK6), cyclin D1, cyclin E1 and phosphorylated retinoblastoma (pRB1) are key regulators of the G1/S cell cycle checkpoint and may influence platinum response in ovarian cancers." (PMID 38612869, 2024). "Taken together, these data demonstrated that ZC-22 could effectively induce cell cycle arrest and apoptosis through the inhibition of both PARP and CDK4/6 in breast and ovarian cancer cells regardless of HR status." (PMID 35270034, 2022). "Considering these data as whole, we found that a significant fraction of ovarian cancers that have been analyzed display an aberrant expression of cyclins, CDKs and/or CDKI, supporting the hypothesis that these tumors could be potentially sensitive to CDK4/6i." (PMID 34204543, 2021). "However, 17% of ovarian cancer patients in the TCGA database also have homozygous deletions or significantly downregulated RB1; these patients are less likely to receive significant benefit from CDK4/6 inhibitor therapy." (PMID 29644000, 2018). "Interestingly, compared with parental cells, ovarian cancer cells resistant to flavopiridol and cisplatin showed the increased expressions of CDK1, cyclin D3 and Rb, decreased expressions of cyclin B, and equal expressions of cyclin A, cyclin E, CDK2, CDK4." (PMID 25962959, 2015).
colorectal cancer (108 papers, 2007 to 2026). A primary or metastatic malignant neoplasm that affects the colon or rectum. "Among all the CDKs, including CDK1, CDK2, CDK4, and CDK6, CDK4 was defined as an independent risk factor for colorectal cancer." (PMID 34595111, 2021). "In this study, we examined the Cdk4 pathway and its blockade in the context of Apc mutation to determine the potential for targeting this pathway in a chemopreventive strategy for colorectal cancer." (PMID 23530816, 2013). "Molecular alterations associated with CDK4/6 inhibitor resistance in colorectal cancers." (PMID 40699853, 2025). "Here, we have systematically analyzed metabolic reprogramming in colorectal cancer cells exposed to Palbociclib, a CDKi selectively targeting CDK4/6, or Telaglenastat, a selective glutaminase inhibitor." (PMID 40696167, 2025). "Among the upregulated target genes, we highlighted six that are closely linked to colorectal cancer: LGALS9, GLUT1, IGFBP3, CDK4, DUSP1, and HIF1A." (PMID 41411347, 2025). "We then examined the expression levels of c-MYC and its downstream genes (GLUT1 and CDK4) in colorectal cancer cells ectopically expressing STK16 or sgSTK16." (PMID 38622518, 2024). "The CDK4/6 inhibitor Ribociclib has shown limited efficacy as a monotherapy in colorectal cancer (CRC)." (PMID 39769028, 2024). "This study also demonstrated that hub genes (IL1B, GSK3B, NOS3, RELA, and CDK4) were most likely to be involved in the effects of oxidative stress brought on by geniposide in the prevention of colorectal cancer." (PMID 37894904, 2023). "In colorectal cancer, miR-142-3p expression suppressed cell growth through targeting CDK4, indicating that miR-142-3p is a tumor suppressor." (PMID 37009887, 2023). "Our PPI network analysis results showed that IL1B, GSK3B, NOS3, RELA and CDK4 were related to oxidative stress induced by geniposide against colorectal cancer." (PMID 37894904, 2023). "In KRAS mutant colorectal cancer, combinations of CDK4/6 and MEK inhibitors have been found to be synergistic in reducing in vitro cell growth, and to be effective in patient-derived xenograft models." (PMID 37126527, 2023). "In colorectal carcinomas (CRCs), the therapeutic potential of CDK4/6 inhibitors has been evaluated in combination with other drugs, such as immune checkpoint, Raf, and mitogen-activated protein kinase (MAPK) inhibitors." (PMID 36675501, 2023). "In contrast, a previous study has reported that although shUSP1 induced showed G2/M phase arrest in colorectal cancer cells, the authors also showed that shUSP1 can down-regulate CDK4 expression." (PMID 36357365, 2022). "PTPN18 activates myelocytomatosis oncogene (MYC) signaling pathway and further potentiates cyclin-dependent kinase 4 (CDK4) expression to promote colorectal cancer progression." (PMID 35957898, 2022). "In contrast, both CDK4/6 knockdown and palbociclib enhanced glucose metabolism in HCT116 colorectal cancer cells, and elevated glycolysis was also observed in pancreatic cancer cells following CDK4/6 inhibition via palbociclib, abemaciclib and ribociclib." (PMID 33572972, 2021). "Increased glutamine metabolism resulting from CDK4/6 inhibition in breast and colorectal cancer cells has been shown to be dependent on MYC-driven activation of mTOR." (PMID 33572972, 2021). "A CDK4/6 inhibitor (palbociclib) showed a synergistic effect with irinotecan against colorectal cancer." (PMID 33806077, 2021). "In this review, we will focus on the therapeutic role of various CDK inhibitors in colorectal cancer, with a special focus on the CDK4/6 inhibitors." (PMID 35002699, 2021). "Mechanistically, increased glutamine metabolism resulting from CDK4/6 inhibition in breast and colorectal cancer cells has been shown to be dependent on MYC-driven activation of mTOR." (PMID 33572972, 2021).